CDH1 (cadherin 1)
Description:
Cadherins are calcium-dependent cell adhesion proteins. They preferentially interact with themselves in a homophilic manner in connecting cells; cadherins may thus contribute to the sorting of heterogeneous cell types. CDH1 is involved in mechanisms regulating cell-cell adhesions, mobility and proliferation of epithelial cells. Promotes organization of radial actin fiber structure and cellular response to contractile forces, via its interaction with AMOTL2 which facilitates anchoring of radial actin fibers to CDH1 junction complexes at the cell membrane (By similarity). Plays a role in the early stages of desmosome cell-cell junction formation via facilitating the recruitment of DSG2 and DSP to desmosome plaques. Has a potent invasive suppressor role. It is a ligand for integrin alpha-E/beta-7. E-Cad/CTF2 promotes non-amyloidogenic degradation of Abeta precursors. Has a strong inhibitory effect on APP C99 and C83 production. (Microbial infection) Serves as a receptor for Listeria monocytogenes; internalin A (InlA) binds to this protein and promotes uptake of the bacteria.
Synonyms: CD324; CDHE; UVO; uvomorulin; Arc-1; BCDS1; ECAD; LCAM
Tractability: Small molecule: a structure with a bound ligand is known. Antibody: UniProt places it where antibodies can reach, with high confidence; its Gene Ontology location is reachable by antibodies, with high confidence; UniProt predicts a signal peptide or a membrane-spanning region; the Human Protein Atlas places it where antibodies can reach. PROTAC: UniProt records ubiquitination sites on it; ubiquitination databases record sites on it; its protein half-life has been measured.
Target class: Adhesion
Chemical probes: ML327
Gene: Protein-coding gene on chromosome 16 (68,737,292 to 68,835,540, forward strand). Ensembl gene ENSG00000039068.
Subcellular location: Cell junction, adherens junction; Cell membrane; Endosome; Golgi apparatus, trans-Golgi network; Cytoplasm; Cell junction, desmosome; Secreted
Subcellular location (Human Protein Atlas): Cell Junctions; Plasma membrane; Golgi apparatus
Pathways (Reactome):
Cell-Cell communication: Activation of STAT3 by cadherin engagement; Adherens junctions interactions; Degradation of CDH1; Negative Regulation of CDH1 Gene Transcription; Positive Regulation of CDH1 Gene Transcription; Regulation of CDH1 Function; Regulation of CDH1 mRNA translation by microRNAs; Regulation of CDH1 posttranslational processing and trafficking to plasma membrane; SRC activates STAT3 in a quantitative manner, through Cadherin-11 (CDH11), RAC1 and gp130 (IL6ST)
Developmental Biology: Developmental Lineage of Mammary Gland Luminal Epithelial Cells; Developmental Lineage of Mammary Gland Myoepithelial Cells; Developmental Lineage of Mammary Stem Cells; Epithelial-Mesenchymal Transition (EMT) during gastrulation; Formation of definitive endoderm; Regulation of MITF-M-dependent genes involved in extracellular matrix, focal adhesion and epithelial-to-mesenchymal transition; Transcriptional and post-translational regulation of MITF-M expression and activity
Extracellular matrix organization: Degradation of the extracellular matrix; Integrin cell surface interactions
Disease: InlA-mediated entry of Listeria monocytogenes into host cells
Immune System: Immunoregulatory interactions between a Lymphoid and a non-Lymphoid cell
Programmed Cell Death: Apoptotic cleavage of cell adhesion proteins
Signal Transduction: RHO GTPases activate IQGAPs
Gene Ontology:
Molecular function: ankyrin binding; beta-catenin binding; cadherin binding; cell adhesion mediator activity; cell adhesion molecule binding; gamma-catenin binding; GTPase activating protein binding; identical protein binding; protein binding; calcium ion binding; protein tyrosine kinase binding
Biological process: adherens junction organization; cell-cell adhesion; cell-cell adhesion mediated by cadherin; cellular response to indole-3-methanol; cellular response to lithium ion; desmosome assembly; negative regulation of cell migration; negative regulation of cell-cell adhesion; positive regulation of DNA-templated transcription; positive regulation of protein import into nucleus; positive regulation of protein localization; protein localization to plasma membrane; regulation of gene expression; calcium-dependent cell-cell adhesion; cell migration; cell morphogenesis; cell-cell junction assembly; homophilic cell-cell adhesion; synapse assembly; cell adhesion; cell junction assembly; negative regulation of axon extension; neuron projection development; pituitary gland development; regulation of protein catabolic process at postsynapse, modulating synaptic transmission; and 4 more
Cellular component: actin cytoskeleton; adherens junction; apical junction complex; catenin complex; cell junction; cortical actin cytoskeleton; cytoplasm; cytoplasmic side of plasma membrane; desmosome; endosome; extracellular exosome; extracellular region; flotillin complex; Golgi apparatus; lamellipodium; lateral plasma membrane; membrane; perinuclear region of cytoplasm; plasma membrane; trans-Golgi network; early endosome membrane; endoplasmic reticulum lumen; endoplasmic reticulum membrane; Golgi lumen; Golgi membrane; and 3 more
Genetic constraint (gnomAD): Loss-of-function variants: 32 observed, 83.63 expected, observed/expected ratio (o/e) 0.38, 90% interval 0.29 to 0.51. The upper end of that interval is the gene's LOEUF score, 0.51, which puts it in group 2 of 6, group 1 being the genes least tolerant of losing a copy. Missense variants: 992 observed, 1,170.4 expected, observed/expected ratio (o/e) 0.85, 90% interval 0.8 to 0.89. Synonymous variants: 417 observed, 452.31 expected, observed/expected ratio (o/e) 0.92, 90% interval 0.85 to 1.
Gene-disease validity (ClinGen):
ClinGen rates the evidence that CDH1 causes each of these diseases.
CDH1-related diffuse gastric and lobular breast cancer syndrome (autosomal dominant): Definitive.
familial ovarian cancer (autosomal dominant): No Known Disease Relationship. An instance of ovarian cancer that is caused by an inherited modification of the individual's genome.
Cancer hallmarks: invasion and metastasis (suppresses); invasion and metastasis (promotes); change of cellular energetics (promotes)
Homologues: Orthologues: chimpanzee CDH1 (99% identical), macaque CDH1 (96% identical), rabbit CDH1 (85% identical), pig CDH1 (84% identical), dog CDH1 (82% identical), mouse Cdh1 (81% identical), rat Cdh1 (81% identical), guinea pig CDH1 (80% identical), tropical clawed frog cdh3 (57% identical), zebrafish si:dkey-30c15.12 (35% identical). Paralogues in human: CDH3 (54% identical), CDH2 (47% identical), CDH4 (46% identical), CDH15 (34% identical), CDH6 (31% identical), CDH7 (31% identical), CDH10 (30% identical), CDH12 (30% identical), CDH18 (30% identical), CDH11 (30% identical), CDH8 (30% identical), CDH13 (29% identical), and 21 more.
Diseases named in the same sentence as CDH1 in open-access papers:
CDH1 is named in the same sentence as 775 diseases in open-access papers, as found by Europe PMC text mining. Sharing a sentence is not in itself a finding about the gene and the disease. The quoted sentences say what the papers report.
breast carcinoma (2,345 papers, 1993 to 2026). "We identified and validated patient-derived xenograft (PDX) models of ILC from 122 breast cancer PDX models based on truncating CDH1 mutations and/or low CDH1 mRNA expression." (PMID 41943626, 2026). "To date, no robust evidence supports a substantially elevated risk for malignancies beyond gastric and breast cancer in individuals with germline pathogenic variants in CDH1." (PMID 41528496, 2026). "The variability in cancer risk associated with CDH1 mutations – where some carriers develop gastric cancer, breast cancer, or both – highlights the necessity for a personalized approach to genetic counseling and risk management." (PMID 40366456, 2025). "Mutation data for CDH1 in breast cancer reveals a prevalence of specific missense and truncating mutations, predominantly in LBC." (PMID 40757085, 2025). "The identification and management of individuals with CDH1 gene mutations is critical for reducing cancer risk, particularly in regions such as Saudi Arabia, where genetic cancer susceptibility to breast cancer warrants further attention." (PMID 41049353, 2025). "In particular, data from cBioPortal shows a direct association between decreased CDH1 expression and reduced overall survival in breast cancer patients." (PMID 40757085, 2025). "ZWINT expression was lower in tumor specimens from CDH1-mutant breast cancer patients (total mutation rate: 14.096%)." (PMID 40591167, 2025). "The TCGA Breast Invasive Carcinoma (Firehose Legacy) dataset was accessed via cBioPortal to examine CDH1 mutation frequency and copy number alterations in breast cancer subtypes, with a focus on invasive lobular carcinoma." (PMID 40757085, 2025). "A significant association between CDH1 mutations and increased breast cancer risk is emphasized, particularly in hereditary cases." (PMID 40757085, 2025). "Recent evidence underscores the importance of genetic screening for CDH1 mutations in women with early-onset bilateral lobular breast cancer or a strong family history of breast cancer." (PMID 40366456, 2025). "CDH1 mutations are also closely linked to hereditary diffuse gastric cancer (HDGC), as loss of E-cadherin compromises cell cohesion across tissues, leading to invasive growth patterns in both diffuse gastric and lobular breast cancers." (PMID 40366456, 2025). "CDH1 mutation in breast cancer defines a NK cell infiltrated/activated TME type by releasing the inhibition from NK cell inhibitory receptor KLRG1." (PMID 38241355, 2024). "It has been described that hypermethylation of the CDH1 promoter is the predominant mechanism of E-cad loss in several types of cancer, including breast cancer." (PMID 39728992, 2024). "In terms of genetics, genetic analysis of CTC clusters in breast cancer showed that CTC clusters were significantly associated with cadherin 1 (CDH1) and ESR1 Y537S and D538G mutations." (PMID 38427120, 2024). "Germline deletion or mutation in CDH1 is associated with breast cancer development, and deregulation of E-cadherin in breast cancer shows a worse prognosis and shortened overall survival." (PMID 39270819, 2024). "Hereditary diffuse gastric cancer is an inherited condition that can lead to sporadic diffuse stomach and lobular breast cancers, and is driven by loss of function mutations to the CDH1 gene encoding E-cadherin." (PMID 38521964, 2024). "The CDH1 mutation puts females at risk for a certain form of breast cancer called lobular breast cancer." (PMID 39330508, 2024). "The dysregulation, mutation or transcriptional silence of CDH1 gene probably cause breast cancer development." (PMID 36805828, 2023).
breast carcinoma (continued). "Other genes, such as PTEN (associated with Cowden syndrome), STK11 (associated with Peutz-Jeghers syndrome), neurofibromatosis, and CDH-1 (E-cadherin), are also implicated in breast cancer predisposition." (PMID 37750138, 2023). "This is of interest as CDH1 mutations are strongly present in lobular breast cancer and is consistent with lower scores in lobular compared to ductal tumors." (PMID 37637072, 2023). "KCL617, arising from a breast cancer of apocrine morphology, displayed a frameshift CDH1 mutation in both primary tumour and CSF cfDNA, with additional CDH1 loss of heterozygosity (LOH) in the CSF cfDNA." (PMID 37973922, 2023). "Previous research has shown that CDH1 silencing is a major risk factor in the development and progression of breast cancer, which is accomplished by fostering the hypermethylation of its promoter region." (PMID 36765652, 2023). "Taken together, these results underscore the need for early detection of CDH1 germline mutations to allow for timely initiation of high-risk breast cancer screening, for which breast MRI appears to be effective although beset by false-positive results." (PMID 37758801, 2023). "Evidence suggests that some mixed IC-NST and ILC breast cancers harbour differential E-cadherin (CDH1) mutations between the IC-NST and ILC components." (PMID 35053458, 2022). "Over the past decade, many mechanisms have been identified to cause CDH1 inactivation in breast cancer." (PMID 35464064, 2022). "Lifetime disease penetrance estimates for gastric cancer and breast cancer in patients bearing a P/LP variant in CDH1 are approximately 25–42% and 42–55%, respectively." (PMID 36246616, 2022). "We knocked down GATA3 in the human luminal breast cancer cell line, T47D, and again found that the expression of genes associated with luminal differentiation, such as CDH1 and ESR1, was significantly downregulated." (PMID 34976209, 2022). "In the Oncomine, TIMER, and prognostic analyses, significantly high expression levels of CDH1/2/4/7/11/12/13/15 were observed in breast cancer compared to normal tissue samples, and these were associated with poor DMFS outcomes." (PMID 36315446, 2022). "CDH1/2/4/11/12/13 expressions are significantly increased in breast cancer and are associated with poor clinical prognoses of DMFS." (PMID 36315446, 2022). "Polymorphism in the tumor suppressor TP 53 and cell-cell adhesion CDH1 genes is found to increase susceptibility for breast cancer 23,40." (PMID 36910346, 2022). "CDH1/2/4/11/12/13 were overexpressed in breast cancer and were associated with poor prognoses in the distant metastasis-free survival analysis." (PMID 36315446, 2022). "Since the loss of E-cadherin protein expression is a hallmark of invasive lobular breast cancer (ILBC), special attention is paid to CDH1 gene methylation as a potential mechanism for loss of expression in this special subtype of human breast cancer." (PMID 36139537, 2022). "CDH1 P/LP variants were enriched in specific ethnic populations with breast cancer, gastric cancer, CRC, LBC, DGC, and CSRCC compared to matched ethnicities from gnomADv3." (PMID 34949788, 2022). "We also did not have detailed pathology of the breast cancers in the families of those with familial breast cancer, although a number of families did have confirmed lobular family history, including the family with the CDH1 variant." (PMID 33763779, 2022). "Loss of CDH1 in the breast cancer cell line MCF10A by zinc finger nuclease technology resulted in altered expression of cell–cell adhesion genes." (PMID 35993110, 2022). "Other research also confirms that female with CDH1 mutations have a significant lifetime risk of breast cancer as well as diffuse gastric cancer." (PMID 35927682, 2022). "Nevertheless, evidence from clinical applications such as in vitro data or large patient cohorts should be produced to validate associations between CDH1/2/4/11/12/13 and breast cancer." (PMID 36315446, 2022).
breast carcinoma (continued). "Deregulation of CDH1 function plays a fundamental role in breast cancer metastasis and is associated with a worse prognosis." (PMID 35464064, 2022). "Of the studied variants rs3743674 of the CDH1 gene (crude P=0.014 and adjusted p=0.000) evident significant association with breast cancer in Pakistani Pashtun population." (PMID 36910346, 2022). "The most common cancer types in patients with P/LP CDH1 variants were breast cancer (77 of 141, 54.6%), gastric cancer (56 of 141, 39.7%), and CRC (14 of 141, 9.9%)." (PMID 34949788, 2022). "It is known that in breast cancer E-cadherin is inactivated and is also known that the loss of CDH1 function induces EMT, causing dysregulation of cell–cell adhesion and anoikis resistance." (PMID 36497228, 2022). "As 13/319 of the breast cancer cases analyzed in this series were lobular carcinomas (4.1%), likely- to pathogenic variants in the pleiotropic CDH1 gene would have been missed." (PMID 36568162, 2022). "Our results show a significant association of CDH1 rs3743674 polymorphism with increasing risk of breast cancer in the Pashtun population of Pakistan." (PMID 36910346, 2022). "EMT is characterized by a loss of function of the E-cadherin adhesion protein (CDH1) in epithelial tissues; breast cancer is a good example of this process." (PMID 34201896, 2021). "PI3KCA and CDH1 are two frequently mutated genes in many cancers, including breast cancer, gastric cancer, colorectal carcinoma, and head and neck squamous cell carcinoma." (PMID 34745202, 2021). "Rare CDH1 variants, previously shown to predispose to gastric and breast cancer, were significantly overrepresented in these glioma families (13.3%) versus controls (1.7%)." (PMID 33929593, 2021). "Taken together, miR-23a enhances TGF-β1-associated breast cancer metastasis through influencing the expression of CDH1 and inducing Wnt/β-catenin cascade." (PMID 34804971, 2021). "The cumulative lifetime gastric cancer risk at 80 years of age in carriers of pathogenic CDH1 germline variants was described as 70% for males and 56% for females, whereas that of breast cancer was reported as 42% for females." (PMID 34503169, 2021). "This study highlighted the potential beneficial impact of entinostat for the chemoprevention and/or treatment of gastric and breast cancers carrying CDH1 mutations." (PMID 35008338, 2021). "Among the two patients with breast cancer who achieved SD, one harbored an Akt1E17K mutation with a CDH1 frameshift deletion and another harbored a PIK3CA H1047R mutation with a KRAS missense mutation." (PMID 33723724, 2021). "CDH1 mutations are associated with gastric cancer, breast cancer, colorectal cancer, thyroid cancer, and ovarian cancer." (PMID 34868339, 2021).